FANCE (FA complementation group E)
Description:
As part of the Fanconi anemia (FA) complex functions in DNA cross-links repair. Required for the nuclear accumulation of FANCC and provides a critical bridge between the FA complex and FANCD2.
Synonyms: FACE; FAE
Tractability: PROTAC: UniProt records ubiquitination sites on it; ubiquitination databases record sites on it.
Gene: Protein-coding gene on chromosome 6 (35,452,318 to 35,467,106, forward strand). Ensembl gene ENSG00000112039.
Subcellular location: Nucleus
Subcellular location (Human Protein Atlas): Nucleoplasm; Centrosome; Mitotic chromosome
Pathways (Reactome):
DNA Repair: Fanconi Anemia Pathway
Immune System: PKR-mediated signaling
Gene Ontology:
Molecular function: protein binding
Biological process: interstrand cross-link repair
Cellular component: chromatin; Fanconi anaemia nuclear complex; nucleoplasm; cytosol; nucleus; nuclear periphery
Genetic constraint (gnomAD): Loss-of-function variants: 41 observed, 55.59 expected, observed/expected ratio (o/e) 0.74, 90% interval 0.57 to 0.96. The upper end of that interval is the gene's LOEUF score, 0.96, which puts it in group 4 of 6, group 1 being the genes least tolerant of losing a copy. Missense variants: 600 observed, 622.06 expected, observed/expected ratio (o/e) 0.96, 90% interval 0.9 to 1.03. Synonymous variants: 244 observed, 264.74 expected, observed/expected ratio (o/e) 0.92, 90% interval 0.83 to 1.02.
Gene-disease validity (ClinGen):
ClinGen rates the evidence that FANCE causes each of these diseases.
Fanconi anemia complementation group E (autosomal recessive): Definitive. Fanconi anemia caused by mutations of the FANCE gene.
Homologues: Orthologues: chimpanzee FANCE (99% identical), macaque FANCE (95% identical), dog FANCE (78% identical), pig FANCE (76% identical), rabbit FANCE (72% identical), guinea pig FANCE (71% identical), rat Fance (64% identical), mouse Fance (64% identical), zebrafish fance (29% identical), tropical clawed frog fance (28% identical).
Diseases named in the same sentence as FANCE in open-access papers:
FANCE is named in the same sentence as 60 diseases in open-access papers, as found by Europe PMC text mining. Sharing a sentence is not in itself a finding about the gene and the disease. The quoted sentences say what the papers report.
Fanconi anemia (31 papers, 2012 to 2026). Fanconi anemia (FA) is a hereditary DNA repair disorder characterized by progressive pancytopenia with bone marrow failure, variable congenital malformations and predisposition to develop hematological or solid tumors. "Firstly, 2 of the 3 tumors with elevated signature 3 each had 2 pathogenic germline variants both in HR and Fanconi anemia genes (BRCA2/FANCE, BRCA2/FANCD2)." (PMID 40072012, 2025). "FANCE encodes a critical subunit of the Fanconi Anaemia (FA) nuclear complex, which facilitates DNA repair, replication, and chromosome segregation." (PMID 35954343, 2022). "BRIP1 and variant rs4986765 are related to familial cancer of the breast, neoplasms of the ovary, hereditary cancer-predisposing syndrome, and Fanconi anemia, which is also associated with the variant rs4713867 (FANCE) gene." (PMID 32708070, 2020). "Two candidate genes within the linkage interval for MCHC include HFE, to which multiple MCH, HB, and HCT associations have been reported; and FANCE, a Fanconi anemia gene." (PMID 24058921, 2013). "Notably, upregulation of USP1, RMI2, and FANCE in the 2x load group, associated with the Fanconi anemia pathway, was observed among DNA repair‐related genes." (PMID 40080399, 2025). "These include variants in genes encoding FANCE, a subunit of the Fanconi Anaemia (FA) nuclear complex; NKX2-1, a transcription factor and negative regulator of the NF-κB signalling pathway; and other recognized oncogenes JAK2, PRDM16, BMPR1A and tumor-suppressor genes KMT2C, FAT4, and LRP1B." (PMID 35954343, 2022). "FANCE may be associated with AR Fanconi’s anemia, also a cause of arteriovenous pulmonary fistulae." (PMID 36834577, 2023). "While Fanconi Anemia-associated genes BRCA2, FANCA and PALB2 are known PCa GT candidates, FANCD2 outranked FANCA, with FANCG, ECCR4, FANCE and FANCI (in order of ranking) potential candidates." (PMID 41038821, 2025). "The present study broadens the existing research, most of which focus on the role of FANCE in Fanconi anemia." (PMID 33592580, 2021). "Previous studies showed that ANKRD13B and FANCE were associated with epidermal growth factor receptor (EGFR) activation and Fanconi anemia, respectively." (PMID 34917510, 2021). "Recently, the detection of pathogenic variants in Fanconi anemia DNA damage repair pathway genes, such as BRCA2, BRIP1, FANCC, and FANCE was also reported in familial CRCs34." (PMID 30850667, 2019). "FANCE is included in the Fanconi anaemia complementation group essential for DNA damage repair." (PMID 32277576, 2020). "This analysis identified several novel ATR synthetic lethal partner genes involved in DNA damage/repair including those targeting components of the HR/Fanconi Anaemia pathway (FANCE, SLX4, PALB2), DNA mismatch repair (MSH4, PMS2) and trans-lesion synthesis (RAD18) pathways." (PMID 27958275, 2016). "The most significant SNP on chromosome 26 was located between NGF and FANCE; NGF is known to be involved in nerve growth, while FANCE plays a key role in the Fanconi anemia pathway." (PMID 40427243, 2025). "Deleterious alterations were also identified in nearly all (13/14) tumours in members of the Fanconi anaemia complementation groups, including FANCD2, FANCF, FANCC, FANCA, and FANCE." (PMID 34045664, 2022). "Among DNA repair genes, we detected a high presence of members of the Fanconi Anemia Complementation Group (FANCC, FANCD2, FANCG, FANCA, and FANCE), which participate in homologous recombination DNA repair, and genes involved in double-strand break repair (BRCA2, BRIP1, BARD, BLM, CHEK2, and PALB2)." (PMID 30487452, 2018).
breast carcinoma (8 papers, 2020 to 2023). "FANCE is reported to be a vital factor influencing the poor survival of FANCE-deficient cells among breast cancer cell lines, and upregulation of LMNB2 is associated with significantly poorer prognosis in lung adenocarcinoma patients." (PMID 33499863, 2021). "Different studies have found that FANCE mutations in breast cancer, sarcoma, colorectal cancer, gastric cancer and esophageal cancer, but its impact on the prognosis of these malignancies has not been reported." (PMID 33592580, 2021). "A study analyzed the FANCE splice isoform and found this splice variant is high expressed in breast cancer individuals, and this isoform can be efficiently translated into a functional protein to block into G2/M phase, leading to the reduction of cell survival." (PMID 37168687, 2023). "FANCE expression positively correlated with neoantigens in endometrial cancer, gastric cancer, ovarian cancer, and breast cancer." (PMID 36685883, 2022). "In addition, two patients harbored a PV in a PDAC-predisposition and another gene: ATM/FANCE (PDAC patient with colon cancer) and BRCA2/CHEK2 (early-onset breast cancer PDAC patient)." (PMID 34503238, 2021). "Mutations have been observed in FANCE which have been speculated to facilitate the development of colorectal cancer, and FANCE alternative splicing may impair ICL repair in breast cancer." (PMID 36046263, 2020). "As a result of our research, FANCE expression was positively correlated with TMB in 22 cancers containing endometrial cancer, gastric cancer, ovarian cancer and breast cancer, and so on." (PMID 36685883, 2022). "However, another study could not find a significant link between FANCE mutation and breast cancer." (PMID 36046263, 2020).
ovarian cancer (6 papers, 2008 to 2022). A primary or metastatic malignant neoplasm involving the ovary. "The study by Bonache showed that FANCE was included in the gene set of 18 genes with loss-of-function variants in breast or ovarian cancer patients, three of which also carried pathogenic variants in known cancer genes." (PMID 33592580, 2021). "In ovarian cancer, FANCE was predominantly present in cancer cells, with a minority distributed in fibroblasts, T cells, and macrophages." (PMID 36685883, 2022). "Single-cell sequencing data showed FANCE was primarily expressed in cancer cells in cervical and ovarian cancer, and in fibroblasts in endometrial cancer." (PMID 36685883, 2022). "FANCE expression negatively correlated with stromal/immune scores in 21 cancers including cervical cancer, endometrial cancer, and ovarian cancer." (PMID 36685883, 2022). "FANCE expression in ovarian cancer and endometrial cancer might enhance ICIs therapy response since positively correlated with PD-1 and PD-L1." (PMID 36685883, 2022). "Additionally, the up-regulation of FANCE expression was significantly related to the 5-year survival improvement of patients with thyroid cancer, thymoma, and ovarian cancer." (PMID 33592580, 2021). "FANCE positively correlated with immune checkpoint inhibitors PD-1, PD-L1, and CTLA4 in endometrial cancer and ovarian cancer." (PMID 36685883, 2022).
endometrial cancer (4 papers, 2020 to 2024). Primary or metastatic malignant neoplasm involving the endometrium (mucous membrane that lines the endometrial cavity). "FANCE expression positively correlated with microsatellite instability, tumor mutational burden, and neoantigens in 7, 22, and five cancers, especially in endometrial cancer, potentially increasing the effectiveness of immunotherapy." (PMID 36685883, 2022). "Among previously not reported associations with overall survival were mutations in GATA3 and FANCE genes in colorectal cancer, mutations in gene PTPN11 in glioma, and mutations in RNF43, MSH6 and FBXW7 genes in endometrial cancer." (PMID 39277826, 2024). "Our results showed that in endometrial cancer, FANCE was expressed in cancer cells, fibroblasts, endothelial cells, and T cells." (PMID 36685883, 2022). "FANCE expression negatively correlated with CD8 T cells in endometrial cancer and positively correlated with M1 macrophages in cervical cancer, possibly related to cancer prognosis." (PMID 36685883, 2022). "High FANCE expression in endometrial cancer was correlated with reduced CD8 T cells and raised Treg cells infiltration." (PMID 36685883, 2022). "We also found FANCE is predominantly expressed in fibroblasts and correlated with poor prognosis in endometrial cancer according to scRNA-seq analysis." (PMID 36685883, 2022). "We investigate detailed functions and mechanisms of FANCE in endometrial cancer (EC)." (PMID 37779877, 2023). "Our analysis of endometrial cancer scRNA-seq results showed that FANCE was expressed in T cells." (PMID 36685883, 2022). "FANCE expression was positively correlated with MSI in seven cancers, especially in endometrial cancer and gastric cancer." (PMID 36685883, 2022).
esophageal squamous cell carcinoma (3 papers, 2015 to 2023). Esophageal squamous cell carcinoma (ESCC) is a type of esophageal carcinoma (EC) that can affect any part of the esophagus, but is usually located in the upper or middle third. "In the current study, we found that in cervical squamous cell carcinoma, esophageal squamous cell carcinoma, gastric cancer, lung squamous cell carcinoma, and rectal adenocarcinoma, the up-regulation of FANCE was associated with both a decrease in macrophage enrichment and a better prognosis." (PMID 33592580, 2021). "In five types of tumors: cervical squamous cell carcinoma, esophageal squamous cell carcinoma, gastric cancer, lung squamous cell carcinoma, and rectal adenocarcinoma, high expression of FANCE predicts a good prognosis." (PMID 33592580, 2021). "Increased risk of esophageal squamous cell carcinoma (ESCC) was reported to be associated with mutations in FANCD2, FANCE, FANCL, and FANCA in patients from an Iranian population." (PMID 26596371, 2015).
cervical carcinoma (2 papers, 2016 to 2022). A carcinoma arising from either the exocervical squamous epithelium or the endocervical glandular epithelium. "High FANCE expression in cervical cancer was positively associated with M1 macrophage infiltration, consistent with its favorable prognosis." (PMID 36685883, 2022). "According to our scRNA-seq analysis of cervical cancer cells, FANCE was expressed mainly in cancer cells and less in T cells." (PMID 36685883, 2022). "As a result, more research is needed to explore the relationship between FANCE’s effect on the immune microenvironment and its prognostic value in cervical cancer." (PMID 36685883, 2022). "The role of FANCE in cervical cancer should be further studied." (PMID 36685883, 2022). "In cervical cancer, FANCE expression was positively correlated with PDL1 and CTLA4." (PMID 36685883, 2022). "FANCE staining was higher in prostate, testis, and cervical cancers than in normal tissues." (PMID 36685883, 2022). "In cervical cancer, FANCE was mainly expressed in cancer cells and less abundant in T cells." (PMID 36685883, 2022). "We found FANCE expression correlated with shorter OS and PFI in UCEC and longer OS and PFI in cervical cancer." (PMID 36685883, 2022).
gastric cancer (2 papers, 2021 to 2022). A primary or metastatic malignant neoplasm involving the stomach. "Patients with FANCE defects are at risk of developing esophageal cancer, gastric cancer, and leukemia." (PMID 36685883, 2022).
hepatocellular carcinoma (2 papers, 2021 to 2023). A malignant tumor that arises from hepatocytes. "Although three candidate targets ANKRD13B, LMNB2, and FANCE, which were regulated by miR-326, were all associated with HCC patient survival, only LMNB2 has been investigated in a hepatocellular cancer study before." (PMID 34917510, 2021). "High expression of FANCE in hepatocellular carcinoma (HCC) may promote tumor proliferation by activating cell cycle signaling, and be a biomarker of poor prognosis." (PMID 37779877, 2023).
sarcoma (2 papers, 2020 to 2021). A usually aggressive malignant neoplasm of the soft tissue or bone. "However, in uterine corpus endometrial carcinoma, sarcoma, pheochromocytoma and paraganglioma, high expression of FANCE is significantly associated with poor prognosis." (PMID 33592580, 2021). "Similarly, another study of genome sequencing of 66 patients with sarcoma also found that one patient had FANCE nonsense mutation." (PMID 33592580, 2021).
autoimmune thyroid disease (1 paper, 2022). Inflammatory disease of the thyroid gland due to autoimmune responses leading to lymphocytic infiltration of the gland. "FANCE negatively regulated antigen processing and presentation pathway CESC and positively regulated autoimmune thyroid disease in OV." (PMID 36685883, 2022).
esophageal cancer (1 paper, 2021). A primary or metastatic malignant neoplasm involving the esophagus. "Single nucleotide polymorphisms of FANCE in the DNA repair pathways have been associated with increased risk of esophageal cancer." (PMID 33592580, 2021).
hereditary cancer (1 paper, 2020). Malignant neoplasms occurring in families at a rate greater than that expected by chance and caused by germline mutations in a specific gene. "A prospective cohort of 1021 unrelated cancer cases with clinical suspicion of hereditary cancer was screened for mutations in the following 14 FA genes: FANCA, FANCB, FANCC, FANCD2, FANCE, FANCF, FANCG/XRCC9, FANCI, FANCL/PHF9, FANCM, FANCP/SLX4, FANCQ/ERCC4, FANCR/RAD51 and FANCU/XRCC2." (PMID 32235514, 2020).
multiple sclerosis (1 paper, 2023). A progressive autoimmune disorder affecting the central nervous system resulting in demyelination. "However, looking into our phenotypic data we can verify that CTD (SLC22A5), Parkinson ́s disease (LRPPRC), multiple sclerosis (IL4R), 3-MCCD (MCCC1), and different cancer types (FANCE, MAD1L1 and CD46) have been reported by the participants." (PMID 36404349, 2023).
non-small cell lung carcinoma (1 paper, 2022). A group of at least three distinct histological types of lung cancer, including non-small cell squamous cell carcinoma, adenocarcinoma, and large cell carcinoma. "Patients with the FANCE variant had better prognosis for non-small cell lung cancer." (PMID 36685883, 2022).
prostate adenocarcinoma (1 paper, 2021). "Interestingly, the relationship between FANCE and immune cells in liver hepatocellular carcinoma (LHC), prostate adenocarcinoma (PRAD), breast invasive carcinoma (BRCA), and kidney renal papillary cell carcinoma (KIRP) appears to be completely opposite to that in HNSC." (PMID 33592580, 2021).
renal carcinoma (1 paper, 2022). A carcinoma arising from the epithelium of the renal parenchyma or the renal pelvis. "In addition, FANCE staining was lower in renal cancer than in normal tissues." (PMID 36685883, 2022).
tongue cancer (1 paper, 2021). A malignant neoplasm affecting the tongue. "Wreesmann detected the FA gene expression in 49 tongue cancer specimens and found that downregulation of FANCE in sporadic HNSC was rare." (PMID 33592580, 2021).
xeroderma pigmentosum (1 paper, 2025). Xeroderma pigmentosum (XP) is a rare genodermatosis characterized by extreme sensitivity to ultraviolet (UV)-induced changes in the skin and eyes, and multiple skin cancers. "Other pathogenic variants were present in FANCE, XPA and ERCC5, associated with Fanconi anaemia, xeroderma pigmentosum (XP) group A and XP group G, respectively." (PMID 39315505, 2025).